INS (insulin)
Diseases named in the same sentence as INS in open-access papers (continued):
Sharing a sentence is not in itself a finding about the gene and the disease.
Hyperglycemia (continued). "Negative binomial regression with propensity score-based IPTW showed that the use of SC insulin was associated with higher counts of hyperglycaemia (> 1.8 g/L) (IRR: 3.45 [95%CI 2.97; 4.00]; P < 0.0001)." (PMID 37330419, 2023). "As expected, higher glycaemias were associated with higher SOFA score, i.e., more stress hyperglycaemia and insulin dysregulation." (PMID 37330419, 2023). "T2D leads to hyperglycemia due to various causes, and the main causes are insulin resistance, insulin secretion defects in beta cells, and excessive glucose production in the liver." (PMID 37623224, 2023). "T1DM is an autoimmune disease in which insulin-secreting pancreatic β-cells are targeted, leading to a loss of insulin secretion and subsequent impaired glucose metabolism, causing hyperglycemia." (PMID 37240105, 2023). "The expression of the vitamin D receptor (VDR) in pancreatic beta cells suggests the involvement of vitamin D in insulin production, but the evidence for the association of maternal hyperglycemia with vitamin D status during pregnancy varied." (PMID 38075561, 2023). "Our aim is to emphasize the active role and main outcomes of GLP-1 agonists in promoting weight loss, as well as in improving hyperglycemia, insulin sensitivity, blood pressure, cardio–metabolic, and renal protection." (PMID 37445623, 2023). "We propose that loss of adipose HK2 is a mechanism of diet-induced insulin insensitivity and hyperglycemia." (PMID 36920797, 2023). "Intensifying insulin therapy to minimise hyperglycaemia is important to reduce the risk of long-term macrovascular and microvascular complications." (PMID 37289734, 2023). "We previously reported that only two probands, both un-carriers of the “pesto” mutation, out of 98 GCK/MODY cases (2%) were treated with insulin one year after the first finding of hyperglycaemia." (PMID 36835446, 2023). "Hyperglycemia is common in TS and is probably caused, at least in part, by an intrinsic defect in insulin secretion." (PMID 36875465, 2023). "The present investigation first confirmed that STZ caused sustained hyperglycemia as a result of reduced insulin secretion." (PMID 37081849, 2023). "Insulin plays a crucial role in the regulation of blood glucose levels, with insulin resistance leading to hyperglycemia and acting as a major risk factor for T2DM." (PMID 37059897, 2023). "In contrast, T2DM takes place when the body cannot respond fully to insulin, followed by an increase in insulin production and subsequent insulin deficiency, heading to a permanent hyperglycaemia and glucose intolerance." (PMID 37950274, 2023). "We also look forward to prospective, large-scale randomized controlled studies to determine the efficacy and safety between different insulin infusion methods and provide evidence to optimize the optimal treatment strategies for PN-associated hyperglycemia." (PMID 37674887, 2023). "Hyperglycemia is predominantly caused by reduced insulin sensitivity and cell resistance in insulin-sensitive tissues, such as the liver, skeletal muscle, and fat." (PMID 37432173, 2023). "The loss of GIPR activity in pancreatic beta cells has been associated with hyperglycemia and a decrease in postprandial insulin secretion." (PMID 37510690, 2023). "T2DM is characterized by an increase in blood sugar levels caused by insufficient pancreatic insulin production which as a result leads to hyperglycemia." (PMID 37943820, 2023). "PAX6 also maintains mature mouse beta cell function and identity; while selective PAX6 deletion in adult mouse beta cells impairs insulin secretion and causes progressive hyperglycemia." (PMID 37933577, 2023). "Type 1 diabetes (T1D) is a chronic autoimmune disorder that damages beta cells in the pancreatic islets of Langerhans and results in hyperglycemia due to the loss of insulin." (PMID 37296593, 2023).
Hyperglycemia (continued). "Cardiovascular disease and AS associated with diabetes are dependent not only on hyperglycemia but also on alterations in lipids, changes in hormones in addition to insulin, and a pro-inflammatory state." (PMID 36899843, 2023). "Type 1 diabetes mellitus (T1DM) is one of the most common metabolic disorders that is characterized by the absolute deficiency of insulin and hyperglycemia due to the autoimmune destruction of pancreatic beta (β) cells." (PMID 37893548, 2023). "Type two diabetes (T2D) is caused by defects in both insulin secretion and insulin sensitivity that result in glucose intolerance, increased gluconeogenesis, and hyperglycemia with severe complications." (PMID 36674274, 2023). "The circadian disruptions, indeed, cause an inadequate pancreatic beta cell insulin secretion after a standardized meal, explaining the consequent hyperglycemia." (PMID 36986157, 2023). "Atherosclerosis lowers blood circulation to the pancreas and impairs pancreatic function, which reduces insulin secretion levels and causes hyperglycemia." (PMID 36740459, 2023). "Nevertheless, early introduction of insulin is suggested if there is evidence of ongoing catabolism (weight loss), if symptoms of hyperglycemia are present, or when glycated hemoglobulin levels (>10%) or blood glucose levels (≥300 mg/dL) are very high." (PMID 36650625, 2023). "With respect to the pathophysiology of BD, there was a reduction in the level of insulin, which corresponded with the critically ill condition of the patient, predisposing to hyperglycemia." (PMID 37511814, 2023). "Hyperglycemia-induced higher insulin secretion and hyperinsulinemia are implicated in T2D and cause insulin resistance (IR)." (PMID 36829437, 2023). "Diabetes is a multifactorial disease, usually associated with persistently high glucose levels (hyperglycemia), either due to impaired insulin secretion or action." (PMID 37762083, 2023). "The results of the study showed that insulin treatment had a significant protective effect on offspring exposed to maternal hyperglycemia caused by glucose intolerance and obesity." (PMID 37960204, 2023). "Overexpression of α2A-adrenoreceptors in pancreatic islet cells has been postulated as a mechanism for diminished insulin secretion and postprandial hyperglycaemia among carriers of risk alleles in ADRA2A49." (PMID 37828025, 2023). "Previous studies have found that fasting hyperglycemia (GDM-IFH) is closely associated with liver insulin sensitivity and subsequent liver glucose production, whereas post-load hyperglycemia (GDM-IPH) is closely linked with muscle insulin resistance." (PMID 38250975, 2023). "LPD causes maternal hyperglycaemia through reduced circulating insulin and raised glucose at the time of blastocyst formation." (PMID 36517693, 2023). "As expected, HFD feeding progressively increased body weight, blood glucose, and insulin levels, causing hyperglycemia and hyperinsulinemia, compared to normal chow diet feeding." (PMID 37188647, 2023). "T2DM is associated with hyperglycemia and is caused by defective insulin secretion by pancreatic β-cells and the inability of insulin-sensitive tissues to respond to insulin owing to a complex network of pathological conditions." (PMID 37447287, 2023). "DM is a chronic metabolic disorder characterized by hyperglycemia due to deficiency of insulin secretion or impaired insulin action, affecting millions of people worldwide." (PMID 37242519, 2023). "It should be noted that GLP-1-dependent stimulation of insulin secretion occurs only under conditions of hyperglycemia, and the risk of hypoglycemia is very low." (PMID 38139019, 2023). "Cp synthesis and/or secretion can be altered by inflammation and insulin, and Cp levels are positively associated with hyperglycemia and IR." (PMID 37667364, 2023).
Hyperglycemia (continued). "Caregivers reported knowledge of health outcomes associated with hyperglycaemia and hypoglycaemia (resulting in an attitude of ‘the less insulin the better’ for some parents)." (PMID 37049506, 2023). "Early detection of these factors is crucial to minimize the risk of prolonged hyperglycemia, especially in automatic insulin administration methods such as CSII therapy." (PMID 38093983, 2023). "Due to maternal hyperglycemia and resulting anabolic effects supported by greatly increased fetal insulin levels, there is an increased risk for fetal maladaptation and large for gestational age babies (LGA, birth weight > 90th percentile)." (PMID 36840782, 2023). "The effects of short-term tacrolimus exposure promoting hyperglycaemia and compensatory hyperinsulinemia transition to the pseudo-normalisation of insulin, indicative of the loss of insulin secretory capacity, with evidence of β-cell death." (PMID 36899932, 2023). "Increased blood glucose (hyperglycaemia) develops as a result of deficiencies in both insulin secretion and action, affecting the metabolism of carbohydrates, lipids, and proteins." (PMID 36818748, 2023). "In mice, long-term HFD-feeding causes weight gain and hyperglycemia associated with increased insulin and impaired glucose tolerance and is commonly used in the obese-susceptible C57BL/6J mice or SD rats." (PMID 37233701, 2023). "Recently, a gain-of-function Lrp5 mutation in insulin-deficient mice was shown to fully protect bone mass and strength in prolonged hyperglycemia, to improve peripheral glucose metabolism, and to prevent whitening of brown adipose tissue." (PMID 36947076, 2023). "We also observed that lower SgIo, a 75 g oral glucose tolerance test (OGTT)-derived index for glucose effectiveness, was associated with hyperglycemia in the population independently of blood insulin levels." (PMID 36837857, 2023). "Yet, following streptozotocin (STZ) treatment, which reduces β cell numbers and causes hyperglycemia, transgenic mice exhibited an increase in insulin-positive area/islet and insulin-positive cells/islet compared with WT mice." (PMID 38099492, 2023). "Hyperglycemia is associated with poorer cognitive performance and is caused by dysregulation of insulin and the expression of insulin-degrading enzymes." (PMID 36949414, 2023). "In adults with T1D, low CHO diets have been shown to decrease postprandial hyperglycaemia, improve glycated haemoglobin (HbA1c), increase time in range and reduce hypoglycaemia risk due to reduced insulin requirements." (PMID 37049506, 2023). "DM is characterised by hyperglycaemia and is caused by defects in insulin secretion, insulin action, or both; its varied, biochemical, and clinical manifestations render it one of the most common metabolic diseases in humans." (PMID 36824442, 2023). "The insulin secretion impairment associated with cystic fibrosis determines the hyperglycemia to install." (PMID 37893045, 2023). "Gestational and lactation exposure to phthalates causes hyperglycemia, impaired glucose, and insulin tolerances, and altered insulin transduction pathways in adult male offspring." (PMID 37854189, 2023). "Age per se is one of the most important risk factors in the development of hyperglycemia, leading to both deficiency of insulin secretion and insulin resistance." (PMID 37115218, 2023). "Although reduced insulin action (IR) is implicated in hyperglycemia, some aspects of insulin signaling pathways are preserved in states of IR." (PMID 37008938, 2023). "This innovative approach increased the ratio of β-cells per islet and improved insulin secretion, ameliorating the hyperglycemia associated with this condition." (PMID 37108631, 2023). "This method involves the administration of certain chemicals that cause the destruction of endogenous β-cells, resulting in reduced insulin production, hyperglycemia, and weight loss." (PMID 37859703, 2023).
Hyperglycemia (continued). "Hyperglycemia is caused by reduced glucose utilization, increased glucose production, and decreased insulin secretion." (PMID 37798798, 2023). "On the other hand, exaggerated reduction or even skipping of insulin dosage, as well as consuming excessive amounts of carbohydrates, causes hyperglycemia before and during the exercise, possibly leading to ketosis." (PMID 36981876, 2023). "Hyperglycemia and impaired blood insulin levels impair the neuroprotective properties of insulin in the central nervous system and cause an overproduction of free radicals, which will damage nerve tissue and retinal vessels." (PMID 38202817, 2023). "The phenotype of BB rats is characterized by hyperglycemia, hyperinsulinemia, weight loss, and ketonuria requiring insulin treatment." (PMID 36829539, 2023). "T2DM is a complex metabolic disorder characterised by a progressive loss of b-cell insulin secretion, causing hyperglycemia against a background of insulin resistance." (PMID 37365269, 2023). "Diabetic Mellitus (DM), a chronic metabolic disorder disease characterized by hyperglycemia, is mainly caused by the absolute or relative deficiency of insulin secretion or decreased insulin sensitivity in target tissue cells." (PMID 37732125, 2023). "This suggests that insulin signaling is also inhibited in PC12 cells owing to increased AGE conversion caused by hyperglycemia." (PMID 37571372, 2023). "The development and progression of T2DM include several mechanisms, such as chronic low-grade inflammation, hyperglycemia, insulin secretion deficiency, autophagy dysregulation, electrolyte imbalance, oxidative stress, and disruption of endothelial function." (PMID 37372041, 2023). "With regard to metabolic control, the primary consequence of WT PI3Kα inhibition is to block insulin action (e.g., insulin resistance), impairing glucose disposal and causing hyperglycemia." (PMID 37623743, 2023). "Disorder and reduction in ICC in STZ–NA-induced diabetes mellitus can be caused by hyperglycemia and increased oxidative stress, insulin and insulin-like growth factor deficiency, autoimmune response, or a combination of these factors." (PMID 36837509, 2023). "On the other hand, long-term hyperglycemia caused by the overloading of the pancreas, resulting in the secretion of an excessive quantity of insulin to maintain blood sugar, which leads to impaired pancreatic function and abnormal islet structure." (PMID 37601073, 2023). "Metals impact glucose regulation by disrupting pancreatic β-cells, causing hyperglycemia and impaired insulin signaling." (PMID 37240215, 2023). "Another study showed that the selective elimination of IR in the proximal tubule caused hyperglycemia despite normal insulin sensitivity." (PMID 37675359, 2023). "Concomitant fasting and postload hyperglycemia were associated with the most severe defects in both insulin secretion and insulin sensitivity, followed by those with isolated fasting hyperglycemia who had less severe defects in both indices." (PMID 36950879, 2023). "Defects in insulin production and action cause hyperglycemia and other metabolic abnormalities associated with T2D through uncontrolled hepatic gluconeogenesis and dyslipidemia due to the dysregulation of fatty acid, triglyceride, and lipoprotein metabolism." (PMID 37280499, 2023). "Calcineurin signalling is required for insulin secretion and β-cell proliferation, and the specific inactivation of calcineurin in β-cells is associated with hyperglycaemia with increasing age." (PMID 36899932, 2023). "The control animals developed progressive hyperglycemia and an associated loss of PDx-1 and insulin mRNAs and diminution of glucose-stimulated insulin secretion." (PMID 36834496, 2023). "Maternal hyperglycemia is the cause of increased fetal glucose, which then stimulates the beta cells of the fetal pancreas to produce insulin." (PMID 36771307, 2023).
Hyperglycemia (continued). "The cause of perioperative hyperglycemia is a transitory resistance to insulin leading to a decreased peripheral uptake of glucose." (PMID 36310325, 2023). "This study showed that humans with the solute carrier family 30-member 8 (SLC30A8) risk allele and ZnT8 knockout mice have increased hepatic insulin clearance, which was assessed using the C-peptide-to-insulin ratio and postprandial hyperglycemia." (PMID 38115089, 2023). "In another example, breakfast skipping was associated with impaired insulin response and increased post-prandial hyperglycemia at lunch and dinner." (PMID 36771435, 2023). "The increased risk from hyperglycemia including that of sepsis and multiorgan failure is empirically controlled with intensive insulin therapy." (PMID 37998031, 2023). "Sustained hyperglycemia is well known to largely contribute to the progressive failure of cells and organs, including insulin-secreting cells, and is one of the major causative factors of diabetic complications." (PMID 38203600, 2023). "The occurrence of hyperglycemia and postprandial delayed hypoglycemia is mainly caused by the binding and dissociation of insulin autoantibodies and insulin." (PMID 36844104, 2023). "Type 2 diabetes (T2D) is a metabolic disorder characterized by chronic hyperglycemia caused by disturbances in the action of insulin, insulin secretion, or both." (PMID 36769113, 2023). "Results show increased body weight, hyperglycemia, and reduced plasma insulin levels on KI lineage, indicating that S273A mutation modifies the metabolism of young animals, causing hypoinsulinemia." (PMID 37189379, 2023). "Hyperglycemia due to a defect in insulin secretion in T1D also contributes to an increased risk of cardiovascular events." (PMID 37951886, 2023). "Glucose that passes through the liver causes peripheral hyperglycemia; however, it is difficult for it to be taken up by muscle and adipocytes due to decreased insulin action, and postprandial hyperglycemia is thereby prolonged." (PMID 37762244, 2023). "In Type 1 DM, diabetic cardiomyopathy is mainly caused by persistent hyperglycemia and reduced insulin signaling, while in Type 2 DM, cardiomyopathy is related to both hyperglycemia and insulin resistance." (PMID 37908006, 2023). "T2DM is a metabolic disease characterized by hyperglycemia, i.e., chronically elevated blood glucose levels caused by impaired insulin production and insulin resistance." (PMID 37834960, 2023). "DM is a metabolic disease characterized by hyperglycemia caused by defective insulin secretion or insulin dysfunction." (PMID 37746665, 2023). "Impairment of DNM1 causes insulin secretion failure and hyperglycemia in mice while inhibiting the expression of EP300 reduces adiposity in larval zebrafish." (PMID 37620670, 2023). "We already know that systemic corticosteroids cause hyperglycemia, especially postprandial glucose, with the dysfunction of pancreatic β-cells, causing IR, which raises the need for insulin therapy." (PMID 37187644, 2023). "Hyperglycemia alone can affect insulin secretion, sincehigh glucose levels cause cell desensitization and/or dysfunction (glucosetoxicity)." (PMID 36348712, 2022). "Historically, hyperglycemia has been linked to hyperinsulinemia, the possible reason is that the host requires more insulin to maintain glucose homeostasis." (PMID 35845787, 2022). "One of the biggest contributing factors to of hyperglycaemia is insulin sensitivity, as the elevated insulin and associated blood glucose levels in response to a CHO rich meal are only seen in individuals with IR." (PMID 35529461, 2022). "Other studies have shown that the higher the proportion of insulin use in diabetic patients, the longer the course of the disease, the longer the blood vessels are affected by hyperglycemia, the more serious the damage, thereby increasing the risk of CVD." (PMID 36407464, 2022).